CD38 (CD38 molecule)
Diseases named in the same sentence as CD38 in open-access papers (continued):
Sharing a sentence is not in itself a finding about the gene and the disease.
multiple myeloma (continued). "Daratumumab, a CD38-targeting monoclonal antibody, is a key component of therapy for both newly diagnosed and relapsed or refractory multiple myeloma." (PMID 41568375, 2025). "Tremendous progress has been achieved in multiple myeloma management in the past 25 years with the approval of IMiDs, PIs, and anti-CD38 mAbs, resulting in a major paradigm shift in myeloma treatment." (PMID 39941892, 2025). "The treatment of multiple myeloma has evolved significantly in recent years, with anti-CD38 antibodies (CD38Abs) being a key part of this encouraging development." (PMID 40282438, 2025). "In previously presented studies, this design enabled efficient T-cell engagement and antigen-dependent cytotoxicity against CD38-positive myeloma cells, supporting the feasibility of CD3-redirecting strategies targeting plasma cell antigens." (PMID 41511330, 2025). "Altogether, the further optimization of CARs towards higher efficacy and safety and the adoption of poly-specific approaches unveil new opportunities for expanding the therapeutic window and clinical applicability of CD38-specific products in multiple myeloma." (PMID 40649828, 2025). "The issue of treatment escape and CD38 downregulation following αCD38 antibody treatment has been previously observed in the context of multiple myeloma (MM) when employing this immunotherapeutic targeting strategy." (PMID 40057636, 2025). "For example, ISB 2001 is a trispecific TCE that targets BCMA and CD38 on multiple myeloma cells, plus CD3." (PMID 40702106, 2025). "Daratumumab, an anti‐CD38 antibody widely used in multiple myeloma, has previously been shown to improve autoimmune cytopenias and can induce long‐term remission for ITP refractory to splenectomy and corticosteroids." (PMID 39886060, 2025). "Daratumumab, the first monoclonal antibody targeting CD38, has been approved for use with standard myeloma regimens." (PMID 39996780, 2025). "Daratumumab targets not only CD38+ tumour cells, such as myeloma cells, but also normal CD38+ immunosuppressive B, T and myeloid cells and induces, like anti‐PD1/PD‐L1 therapy, an expansion of activated cytotoxic T cells." (PMID 40769948, 2025). "CD38 is an important target for the treatment of MM, which is highly expressed by myeloma cells, it is also expressed by activated macrophages and appears to play an important role in Listeria defense." (PMID 41204582, 2025). "A low‐affinity CD138 (stimulatory) CAR paired with a high‐affinity CD38 (co‐stimulatory) CAR distinguished myeloma tissue from healthy tissue." (PMID 41292193, 2025). "Anti-CD38 monoclonal antibodies combined with proteasome inhibitors and immunomodulatory drugs have increased the quality of response in myeloma patients, and MRD evaluation is also entering routine clinical practice in many hematological centers." (PMID 40005973, 2025). "A recent study demonstrated that FT538 iPSC‐NKs in combination with daratumumab (an anti‐CD38 monoclonal antibody) are highly effective against multiple myeloma." (PMID 39797701, 2025). "The cost of most drugs used in multiple myeloma is approximately 100,000 dollars per year and combination regimens with a Proteosome inhibitor, immunomodulatory agent, and an anti CD-38 targeted monoclonal antibody costs 300,000—600,000 US dollars per year." (PMID 39754658, 2025). "The basic phenotypic profile of myeloma cells is distinguished from normal PCs by a CD38-dim CD138-bright expression pattern, together with cytoplasmic light chain kappa or lambda restriction." (PMID 40977723, 2025). "CD38 is a marker for multiple myeloma cells, but it is also expressed by other tumors, although at lower levels." (PMID 39996780, 2025). "Solid tumors typically exhibit lower or heterogeneous CD38 expression compared with multiple myeloma, potentially limiting the efficacy of this targeted-based mechanism of action over non-targeted IFN." (PMID 41445795, 2025).
multiple myeloma (continued). "CD38 is a prognostic marker in chronic myeloid leukemia, and a target in multiple myeloma immunotherapy." (PMID 39996780, 2025). "The capacity of CD38-specific BARs to induce CDC ex vivo was tested on fresh bone marrow cells from five multiple myeloma patients." (PMID 41254160, 2025). "Monoclonal antibodies targeting CD38, such as daratumumab and isatuximab, have shown substantial success in treating multiple myeloma and are being explored for other malignancies." (PMID 40702106, 2025). "Results showed significantly higher uptake of CD38‐EVs by both RPMI8226 and U266 cells at 8 and 12 h, as confirmed by laser scanning confocal microscopy (LSCM), which showed the internalisation of CD38‐EVs into myeloma cells." (PMID 40317915, 2025). "Daratumumab, a monoclonal antibody that specifically targets the CD38 antigen, has emerged as an effective therapeutic option for AL amyloidosis." (PMID 40606777, 2025). "In particular, immunotherapy has changed the outlook for patients with multiple myeloma, because the approval of anti-CD38 mAbs daratumumab (Dara) and isatuximab (Isa)." (PMID 38421887, 2024). "Panobinostat, MS-275, and ACY1215 enhance CD38 expression, thereby increasing daratumumab's anti-myeloma effectiveness." (PMID 38654286, 2024). "This technique was initially used to disrupt the CD38 gene in primary NK cells, aiming to prevent NK cell cannibalism in combination with daratumumab (anti-CD38) because CD38 is expressed in NK cells, multiple myeloma, and acute myeloid leukemia (AML) cells." (PMID 38221520, 2024). "CD38-targeting immunotherapy is approved in combination with lenalidomide and dexamethasone in patients with newly diagnosed multiple myeloma (NDMM) that are transplant ineligible (TI) and is considered the best standard of care (SOC)." (PMID 38830994, 2024). "An alternative depletion approach currently under evaluation for IgAN and adapted for the treatment of multiple myeloma is CD38 depletion." (PMID 39408691, 2024). "CD38’s prognostic significance created therapeutic interest and the mAb CD38 antibody DARA is approved for use as a combinatorial treatment in multiple myeloma." (PMID 39474602, 2024). "CD38 is also found on plasma cells and is highly expressed on multiple myeloma cells; therefore it is targeted by several therapeutic monoclonal antibodies (mAbs), such as daratumumab and isatuximab." (PMID 39575239, 2024). "This novel agent, [68Ga]Ga‐AJ206, possesses the essential characteristics necessary for clinical application, as it delivers high‐contrast CD38‐specific images across various multiple myeloma models." (PMID 38421139, 2024). "Isatuximab is an IgG1κ-derived monoclonal antibody against CD38 approved for the treatment of adult patients with multiple myeloma." (PMID 39246802, 2024). "Modakafusp alfa (TAK-573) is an anti-CD38 ADC consisting of two attenuated IFNα2b molecules attached to an anti-CD38 IgG4 mAb that drives preferential IFNα signaling in myeloma cells." (PMID 38892379, 2024). "In the treatment of multiple myeloma, daratumumab was reported to reduce circulating CD38+ NK cells in a dose-dependent manner." (PMID 39207194, 2024). "The combined use of proteasome inhibitors, thalidomide analogs, and CD38-targeting monoclonal antibodies currently represents the mainstay of modern myeloma therapy." (PMID 38502423, 2024). "Specifically, CD38high myeloma cells were rapidly eliminated by daratumumab via immune selection, indicating that the remaining myeloma cells had lower CD38 expression levels." (PMID 38284882, 2024). "It is indicated for patients who have undergone four or more lines of therapy, including treatment with three major types of multiple myeloma medications: an anti-CD38 monoclonal antibody, a proteasome inhibitor, and an immunomodulating agent." (PMID 38438559, 2024). "Regarding results in primary myeloma cells, tinostamustine only moderately increased CD38 in some patients with low basal expression of this molecule." (PMID 38731936, 2024).
multiple myeloma (continued). "Here, we assessed the effect of tinostamustine on the expression of CD38 and ligands for activating NK cell receptors in MM cells and subsequently explored its potential to enhance the anti-myeloma effect of daratumumab in preclinical models." (PMID 38731936, 2024). "Given the significant enrichment of CD38+-expressing malignant plasma cells, the initial drug development of daratumumab was in multiple myeloma." (PMID 39207194, 2024). "Even so, these CAR T cells effectively killed myeloma cells in model systems, in line with prior knockout mouse studies suggesting that CD38 is generally dispensable for T cell function." (PMID 38800372, 2024). "Considering that a moiety of the tinostamustine molecule has HDAC inhibitor activity, our data are consistent with previous observations that epigenetic drugs such as DNMT or HDAC inhibitors increase CD38 expression in myeloma cells." (PMID 38731936, 2024). "We anticipate these findings will have utility in deriving new strategies to enhance CD38-targeting therapies in myeloma, including mAbs in current clinical practice as well as emerging antibody and cellular therapies." (PMID 40453054, 2024). "Blocking CD38 with anti‐CD38 mAb inhibits the differentiation of mature osteoclasts from multiple myeloma patients' mononuclear cells." (PMID 39180173, 2024). "The discovery that the ectoenzyme CD38 was highly expressed on the cell surface plasma cells led to one of the most significant therapeutic advancements in myeloma of the past decade – the advent of anti-CD38 targeting antibodies." (PMID 38800372, 2024). "We next performed in vitro cell interaction experiments using CD3+ T cell line (Jurkat), CD38+ myeloma cell line (NCI-H929), and CD38-cell line (K562)." (PMID 38280847, 2024). "In multiple myeloma (MM), a cancer of malignant bone marrow plasma cells, cluster of differentiation 38 (CD38) is overexpressed." (PMID 38480650, 2024). "The CD38-targeted construct successfully restored the functionality of dysfunctional NK cells, resulting in the elimination of CD38+ multiple myeloma cells and significant tumor growth inhibition in mouse models." (PMID 39911822, 2024). "In multiple myeloma, daratumumab’s pharmacodynamic activity was observed in circulation in which a significant decrease in CD38 expression was observed on immune cells." (PMID 39207194, 2024). "Taken together, our multiomic studies comprise a resource that reveals new insight into the genetic, epigenetic, and pharmacologic regulation of surface CD38 in myeloma plasma cells." (PMID 40453054, 2024). "Perro and colleagues develop a CD3+ T cell engager co-targeting BCMA and CD38 to improve immunotherapy for multiple myeloma, demonstrate cytotoxicity in patient-derived samples and murine models and develop a quantitative systems pharmacology model." (PMID 39261676, 2024). "Overexpression of CD38 is seen in various hematological malignancies, especially in multiple myeloma." (PMID 38912057, 2024). "In eight of these, we examined 12 surface markers commonly used in myeloma research, while in four cases we studied only a subset of them (CD38, CD44, CD45, CD49d, CD69, CD86, CD138, and CD184)." (PMID 39493694, 2024). "A CD38 monoclonal antibody (daratumumab, used in a clinical trial to treat patients with multiple myeloma) suppressed osteoclastogenesis and bone resorption induced by RANKL in monocytes derived from patients with multiple myeloma." (PMID 39682719, 2024). "Tinostamustine increases CD38 expression in myeloma cell lines, an effect that occurs in parallel with an increment in CD38 histone H3 acetylation levels." (PMID 38731936, 2024). "This systematic review examines the available clinical data on CD34+ cell mobilization, collection, and engraftment in multiple myeloma patients treated with the anti-CD38 monoclonal antibodies daratumumab and isatuximab in clinical trials and in real life." (PMID 39065794, 2024).
multiple myeloma (continued). "The human anti-CD38 monoclonal antibody daratumumab was developed to target plasma cells which express high levels of CD38, and is currently licensed for treatment of the plasma cell malignancy, myeloma." (PMID 38866568, 2024). "Our work provides a resource to design strategies to enhance efficacy of CD38-targeting immunotherapies in myeloma." (PMID 40453054, 2024). "In the treatment of multiple myeloma, the malignant cell expresses CD38, and therapeutic targeting with daratumumab has single-agent activity and improved outcomes in multiple combinations." (PMID 39207194, 2024). "Modakafusp alfa (formerly TAK-573) is a cytokine that delivers interferon-α2B directly to CD38-positive myeloma cells via anti-CD38 T cells (the interferon binds to a different epitope than that to which anti-CD38 monoclonal antibodies bind)." (PMID 39272790, 2024). "Due to the advent of novel agents such as proteasome inhibitors (PI), immunomodulatory agents (IMiD), and anti-CD38 monoclonal antibodies (MoAb), the survival of patients with multiple myeloma (MM) has improved and is expected to continue to improve." (PMID 38660139, 2024). "Monoclonal antibodies against CD38 have been shown to inhibit osteoclastogenesis in multiple myeloma patients." (PMID 39180173, 2024). "We next assessed the in vivo antitumor killing efficacy of BsAbs targeting CD47 and CD38 in a mouse xenograft model using CB17-SCID mice implanted with the NCI-H929 multiple myeloma cell line." (PMID 38983860, 2024). "CD38 is highly expressed in malignant myeloma cells, making it an attractive therapeutic target for CAR-T cell therapy." (PMID 38783333, 2024). "Secondary analysis of data from the Multiple Myeloma Research Foundation (MMRF) CoMMpass study showed that the CD38 expression remained high among relapsed refractory (R/R) MM patients." (PMID 38480650, 2024). "CD38, a well-established target in multiple myeloma therapy, has also been studied in certain subsets of T-cell lymphomas, most notably extranodal NK T-cell lymphoma (ENKTL)." (PMID 39456582, 2024). "Daratumumab, a human IgGκ monoclonal antibody targeting CD38, is mainly used in patients with multiple myeloma." (PMID 38858270, 2024). "ISB 2001 is a CD3+ T cell engager (TCE) co-targeting BCMA and CD38 designed to improve cytotoxicity against multiple myeloma." (PMID 39261676, 2024). "A previous study showed that treatment with the CD38 monoclonal antibody (daratumumab) in multiple myeloma patients reduced autoantibodies in five out of six patients." (PMID 39682719, 2024). "Daratumumab, a United States Food and Drug Administration-approved monoclonal antibody, targets a specific CD38 epitope and is well tolerated and efficacious in multiple myeloma (MM)." (PMID 39046511, 2024). "While nanocarriers can be engineered to recognize molecular markers on myeloma cells, such as CD38, CD1, BCMA, and CD138, tumor heterogeneity and the dynamic nature of these markers can complicate this strategy." (PMID 38254683, 2024). "The study has proven the agent effective against various myeloma cell lines in vitro, showing higher efficacy compared to the commercially available anti-CD38 agent-daratumumab." (PMID 38672662, 2024). "This is the first meta-analysis of randomized clinical trials to evaluate the efficacy and safety of anti-CD38 therapy for the treatment of patients with relapsed or refractory multiple myeloma." (PMID 38672988, 2024). "Preclinical research confirms the activation of interferon signaling in CD38-positive myeloma cells, resulting in anti-proliferative effects and direct and indirect immune cell activation." (PMID 39272790, 2024). "We first sought to use an unbiased approach to identify regulators of surface CD38 in myeloma tumor cells." (PMID 40453054, 2024). "This is illustrated by HTB-1802, the only sample resistant to SAR442257 with high multiple myeloma cell CD38 expression that contained a low E:T ratio." (PMID 38421887, 2024).
multiple myeloma (continued). "These doses are chosen because they have been previously published to significantly increase myeloma surface CD38 by flow cytometry." (PMID 40453054, 2024). "Daratumumab and isatuximab, anti-CD38 MoAbs, are employed in multiple myeloma treatment due to the high expression of CD38 on neoplastic plasma cells." (PMID 38541800, 2024). "We demonstrate this platform by preparing a stable DAR‐6 ADC (TE‐1146) targeting CD38 (UniProt: P28907), a protein overexpressed in multiple myeloma (MM) compared to normal cells." (PMID 38477561, 2024). "Activation of the TBK1-IFN pathway by MEDI2228 enhances CD38 expression in multiple myeloma cells, thereby augmenting the anti-tumor effects of CD38-targeting antibody-drug conjugates." (PMID 39161768, 2024). "Daratumumab is used for treating multiple myeloma (MM), a malignancy arising from CD38 high plasma cells." (PMID 38680487, 2024). "ISB 2001 is a trispecific T-cell engager that redirects cytotoxic T cells via binding to CD3 to BCMA as well as CD38 expressing myeloma cells." (PMID 38660139, 2024). "Daratumumab, a humanized mAb targeting CD38, was first approved for the treatment of multiple myeloma and is currently being investigated for SLE and other conditions." (PMID 39472388, 2024). "Daratumumab is an antibody against CD38 used for plasma cell depletion in relapsed or refractory multiple myeloma (MM)." (PMID 38517598, 2024). "During the last decades, advances in anti-myeloma therapeutics, including proteasome inhibitors, immunomodulatory drugs, and anti-CD38 monoclonal antibodies have considerably improved the treatment outcome in myeloma." (PMID 38280104, 2024). "These concepts were further demonstrated by van der Schans at al. who designed a dual split CD38/CD138 CAR for targeting multiple myeloma." (PMID 39606234, 2024). "Work by others also recently showed that KDM6A knockout can lead to CD38 transcript downregulation in myeloma models." (PMID 40453054, 2024). "The landscape of multiple myeloma (MM) treatment has been recently reshaped by the introduction of anti-CD38 monoclonal antibodies (MoAbs) daratumumab and isatuximab." (PMID 39065794, 2024). "In light of stable expression of CD38 in multiple myeloma cells, it is encouraging to use daratumumab to guide delivery of radionuclides to them." (PMID 38826403, 2024). "Using the high affinity CD38 binder enabled recognition and killing of multiple myeloma cells taken from patients previously treated with the anti-CD38 monoclonal antibody daratumumab who have decreased levels of CD38 expression." (PMID 39606234, 2024). "CD38 is highly expressed on the surface of multiple myeloma cells, and daratumumab, which targets the surface protein CD38 on these cells, has shown single-drug efficacy in relapsed/refractory myeloma." (PMID 39682724, 2024). "Isatuximab is an IgG1 monoclonal antibody that targets a unique epitope of CD38, a transmembrane glycoprotein uniformly expressed on myeloma cells." (PMID 39609425, 2024). "The anti-CD38 monoclonal antibody Daratumumab is approved for the treatment of multiple myeloma but efficiency is curtailed by secondary resistance." (PMID 38355622, 2024). "CD38 is a multifunctional molecule involved in health and diseases, such as chronic lymphocytic leukemia, myeloma and ovarian carcinoma." (PMID 38982370, 2024). "Our findings provide compelling evidence that incorporating anti-CD38 therapy into the treatment regimen of multiple myeloma (MM) patients significantly improves PFS." (PMID 38672988, 2024). "CD45−/CD38+/LILRB4+ and CD45−/CD38+/LILRB4− myeloma cells from the same patient were sorted, and the same number of cells were injected into NSG mice by intratibial injection, respectively." (PMID 38951916, 2024). "The emergence of proteasome inhibitors, immunomodulatory drugs, and anti-CD38 monoclonal antibodies has improved the prognosis of multiple myeloma patients." (PMID 37779413, 2024).